TREM2 (triggering receptor expressed on myeloid cells 2)
Diseases named in the same sentence as TREM2 in open-access papers (continued):
Sharing a sentence is not in itself a finding about the gene and the disease.
dementia (118 papers, 2010 to 2026). Loss of intellectual abilities interfering with an individual's social and occupational functions. "Homozygous mutations in TYROBP (encoding the TREM2 ligand DAP12) or TREM2 cause Nasu–Hakola disease associated with progressive, early-onset dementia, bone cysts, and demyelinating lesions in the CNS." (PMID 40400621, 2025). "Variants in the triggering receptor expressed on myeloid cells 2 (TREM2) gene, which modulates microglial activation, have been identified in populations with high dementia risk and associated with an increased risk for late-onset AD." (PMID 41300248, 2025). "None of the AD patients tested positive for the assayed TREM2 genotype (rs75932628), weakening support for a role for the TREM2 mutation in AD pathogenesis and as a link between osteoporosis and dementia." (PMID 40700291, 2025). "For instance, loss-of-function mutation in TREM2 leads to dementia, and a rare R47H mutation in TREM2 is a risk factor for developing AD." (PMID 39500353, 2024). "A variety of factors have been considered for their possible influence on IBA1 levels in the context of AD, including APOE and TREM2 risk variants, dementia, AD histopathology, and AD Braak staging." (PMID 39135132, 2024). "In Nasu‐Hakola disease, a rare loss of function mutation to Trem2 results in early on set dementia as well as polycystic osseous lesions with recurrent bone fractures." (PMID 38825965, 2024). "Another study on CSF TREM2, reported higher levels of TREM2 in patients with dementia associated with a slower increase of Aβ and lower tau levels, thus suggesting an initial neuroprotective effect of TREM2-positive microglia." (PMID 35250459, 2022). "We supplement existing data by identifying a novel blood CpG correlate of plasma TREM2 levels (cg02521229) located near MS4A4A that previously associated with dementia risk in Generation Scotland participants." (PMID 35475137, 2022). "Microglial involvement in dementia pathogenesis was revealed through a discovery that a rare variant of the gene encoding TREM2 confers several-fold increased risk of AD in humans." (PMID 36145091, 2022). "While Trem2 variant R47H is largely associated with late-onset AD, Trem2 variant Y38C is associated with the development of early onset dementia." (PMID 35685772, 2022). "The genetic associations of Trem2 loss-of-function variants (e.g. R47H) with AD and other forms of dementia highlight the essential role of microglial Trem2 in maintaining homeostasis in brain." (PMID 34504493, 2021). "Gene variants of triggering receptor expressed on myeloid cells-2 (TREM2) are associated with an increased risk of developing dementia." (PMID 34831089, 2021). "Loss‐of‐function genetic variants of triggering receptor expressed on myeloid cells 2 (TREM2) are linked with an enhanced risk of developing dementias." (PMID 31907987, 2020). "Microglia, the resident immune cell of the brain, express TREM2, and microglial responses are implicated in dementia pathways." (PMID 31907987, 2020). "Genetic linkage of TREM2 variants to other dementias reinforces the importance of TREM2-function for cognitively normal aging." (PMID 32985583, 2020). "To understand how loss of functional TREM2 confers predisposition to early-onset dementia, we used Trem2Y38C/Y38C and Trem2−/− mouse models to study neuronal pathology at a developmental and 6 months age." (PMID 33115519, 2020). "This suggests TREM2 impacts neuronal functions providing molecular insights on the predisposition of individuals with TREM2 variants resulting in presenile dementia." (PMID 33115519, 2020). "Another manifestation in NHD patients with TREM2 dysfunction is development of FTD-like dementia with distinct white matter loss." (PMID 33115519, 2020). "The phenotypic transformation from homeostatic microglia towards reactive microglia in dementia pathologies is associated with TREM2, HLA-DRA, ENTPD1 (CD39), CD80 (B7-1), CD86 (B7-2), CCR5, CD274, ITGAX (CD11c), TIMD4 and MRC1." (PMID 33113879, 2020).
dementia (continued). "Because Aβ and Aβ-plaques are believed central to the pathogenesis of AD, it is postulated that TREM2 mutations reduce TREM2 function and increase dementia risk by hampering the anti-amyloidogenic activity of microglia." (PMID 32139718, 2020). "It is also important to note that this variant is located in the extracellular domain of the protein, possibly reducing TREM2 cell surface expression or affecting ligand binding, thus increasing the risk of neurodegeneration and early‐onset dementia." (PMID 32935933, 2020). "A common clinical manifestation in NHD patients and some of the genetic variants of TREM2 or TYROBP is early-onset dementia." (PMID 33115519, 2020). "Our findings with the NOTCH3 and TREM2 variants suggest that mutations in the same gene can result in dissimilar types of dementia." (PMID 30924900, 2019). "A hypomorphic variant of TREM2 is associated with elevated risk of late-onset AD in humans while TREM2 loss of function mutations as associated with dementia, and mice deficient in TREM2 develop AD-associated pathologies." (PMID 31143184, 2019). "Triggering receptor expressed on myeloid cells 2 (TREM2) is linked to dementia and neurodegenerative disease." (PMID 30390679, 2018). "Trem2 expression is known to be critical for clearance of neuronal debris and loss of function of Trem2 or Tyrbp (Dap12) are associated with dementias characteristic of neocortical degeneration observed in AD." (PMID 29681904, 2018). "Variants of TREM2 are known as dementia risk factors linking TREM2 to age-related neurodegeneration." (PMID 30390679, 2018). "To investigate the effects of dementia-causing TREM2 missense mutations on human macrophage function, we took advantage of a recently developed protocol to derive macrophages from human induced pluripotent stem cells (iPSCs)." (PMID 30157425, 2018). "Heterozygous expression of a variant that affects TREM2 splicing in intron 1, which is associated with early onset dementia, also affected the expression of the common variant allele of TREM2, reducing it by more than half." (PMID 28768545, 2017). "Further studies on the TREM2-associated risk of AD indicated that it is the recessive loss-of-function mutations in TREM2 that were responsible for early-onset dementia." (PMID 27313629, 2016). "By performing autozygosity and exome sequencing analyses in Turkish dementia families we identified TREM2 homozygous mutations causing frontotemporal dementia." (PMID 25113539, 2014). "TREM2 had previously been associated with Nasu-Hakola disease, a rare autosomal recessive form of dementia presenting with bone cysts." (PMID 25113539, 2014). "And particularly after the identification of TREM2 homozygous mutations causing frontotemporal dementia, we extended the genetic analyses of this gene to other forms of dementia." (PMID 25113539, 2014). "Due to the common thread of dementia in these homozygous mutations, it was these initial findings that spurred further research to search for heterozygous mutations in the TREM2 gene in AD subjects." (PMID 23533697, 2013). "Recently, the role of microglia and perinatal inflammation has been associated with certain psychiatric disorders while loss-of-function mutation of TREM2 has been associated with several neurodegenerative disorders or dementia." (PMID 23977213, 2013). "However, owing to the low allele frequency of the TREM2 variants, only 58 carriers developed incident dementia, limiting our ability to make a conclusive statement." (PMID 40061357, 2025). "Our literature review reveals 16 TREM2 mutations causing early‐onset dementia and bone lesions." (PMID 38888203, 2024). "Increased TREM2 mRNA expression was described in peripheral blood mononuclear cells from mild cognitive-impaired patients that later converted to AD, as well as in blood from subjects with an increased risk to develop dementia." (PMID 37239970, 2023).
dementia (continued). "In 2013, after identifying triggering receptor expressed on myeloid cells 2 (TREM2) homozygous mutations as the cause of atypical frontotemporal dementia in three Turkish families we expanded the genetic analyses of this gene to include other dementias." (PMID 35000612, 2022). "Interestingly, homozygous missense mutations of TREM2 (a microglial receptor) are linked with increased risk of dementia, while Trem2 p.T66M knock-in mice display an age-dependent reduction in microglial activity, CBF, and brain glucose metabolism." (PMID 35201268, 2022). "Furthermore, a compound heterozygous alteration of the TREM2 gene was identified in one patient and in two patients we found RDVs in other autosomal dominantly inherited genes also associated with dementia (CSF1R-ALSP, PRNP-CJD)." (PMID 35752680, 2022). "Humans with TREM2 deficiency develop the Nasu-Hakola syndrome, characterised by dementia and bone cysts, while several Trem2 KO mice show various – sometimes contradictory – phenotypes due to alterations of expression in other genes beyond Trem2 (e.g. Trem1L) in some models." (PMID 33823896, 2021). "Using these mouse models, transcriptomics data analysis at 6 months indicated alterations in genes and pathways associated with neuronal functions and oligodendrocyte/myelin, thus presenting mice models that mimic physiological conditions of patients with TREM2 variants with FTD-like dementia." (PMID 33115519, 2020). "However, on the same chromosome, it has been shown that TREM2 is associated with some types of dementia, particularly in patients with a behavioral variant frontotemporal phenotype." (PMID 32935933, 2020). "The synaptic dysfunction along with oligodendrocyte/myelin impairment observed at 6 months in Trem2Y38C/Y38C and Trem2−/− mice could help explain why Trem2 variants are predisposed to early onset dementia." (PMID 33115519, 2020). "Indeed, carrying a loss of function mutations in the TREM2 gene represents an important risk factor for dementia." (PMID 31749696, 2019). "One DS participant (D4, 39 years old) with TREM2 R47H (T allele) who was heterozygous for ApoE (ɛ3/ɛ4) slowly deteriorated and developed dementia, whereas another DS participant (D7, 37 years old) who was homozygous for ApoE (ɛ3/ɛ3) but had no clinical symptoms of dementia as yet." (PMID 30909239, 2019). "Studies found the mutation in TREM2 is related to an autosomal recessive form of dementia." (PMID 31366155, 2019). "Moreover, a variable dose of a particular mutation (ie, TREM2 Q33X) can cause different types of dementia." (PMID 30924900, 2019). "We reveal an unexpected potential role of Trem2 in the homeostasis of endothelial cells that goes beyond its known functions as a microglial receptor and signaling hub, suggesting an underlying link between immune response and vascular disease in dementia." (PMID 29906661, 2018). "Additionally, TREM2, primarily located on microglial surfaces, plays a crucial role in phagocytosis and the inflammatory response, with loss-of-function mutations resulting in early onset dementia, including Nasu-Hakola disease." (PMID 39323915, 2024). "In a study of another gene, namely TREM2, single nucleus RNA sequencing of microglia from patients carrying the TREM2 R47H mutation and from sporadic AD patients revealed the existence of a new subset of microglia, designated as amyloid-responsive microglia, specifically involved in dementia." (PMID 37160649, 2023). "Whether there is a relationship between the risk for regression and the later risk of dementia is unknown and specifically whether there are genetic markers that affect the vulnerability to dementia (e.g., ApoE genotype and soluble TREM-2) are also associated with regression." (PMID 34573218, 2021).
dementia (continued). "Alongside these studies, it will also be crucial to investigate the effect of the host on tau oligomer formation; for factors like the genetic makeup such as APOE and TREM2 alleles also affect tau oligomers and thus contribute to determining the risk for neurodegeneration and late-life dementia." (PMID 31608324, 2019). "Notably, several dementia genes are linked to microglia/immune function (e.g. TREM2 and CD33)." (PMID 30252044, 2018). "Given the low allele frequencies of the TREM2 risk variants and younger age of the participants, only one of the 174 TREM2 R47H carriers and five out of the 518 R62H carriers developed dementia." (PMID 40061357, 2025). "The connection between this pathway and major risk factors for dementia such as APOE, TREM2, c9orf72 highlights cGAS-STING pathway as a common convergence point in neuro-immune axis, affecting disease onset and progression." (PMID 41300248, 2025). "While the role of TREM2 in AD and related dementias has been well studied, little attention has been given to the role of TREM2 in the skeletal system." (PMID 38825965, 2024). "Future work aims to address potential interactions of MS4A and TREM2 pathways at further time points in dementia progression and with respect to the outcomes on diverse concomitant neuropathology such as vascular comorbidities." (PMID 38760857, 2024). "Given BRI2’s role in regulating Aβ-Precursor-Protein and TREM2 functions, it holds promise as a therapeutic target for AD and related dementias." (PMID 38347225, 2024). "Two of the three most frequently identified genes in recent exome-wide association studies in unrelated individuals (TREM2 and SORL1) were significantly associated with proxy AD/dementia in this study and the third gene (ABCA7) was nominally significant." (PMID 36750708, 2023). "In order to highlight variants of interest within TREM2 and SORL1, we investigated all variants in these genes which were moderately associated (P < 1 × 10−4) with proxy AD/dementia in the discovery and replication analyses." (PMID 36750708, 2023). "The TREM2 receptor has been connected to various pathophysiology in brain diseases such as dementia, and TREM2 signaling is involved in the regulation of critical microglial functions encompassing proliferation, cytokine release, survival and metabolism." (PMID 37751068, 2023). "More pertinent to this study, TREM2 protein levels correlate with MMP10 levels in patients with dementia." (PMID 36305000, 2022). "We primarily used CD68 as a marker of phagocytic microglia, as well as other markers of microglia including Iba‐1 and TMEM119, and the myeloid cell marker TREM2 to assess dementia‐specific changes." (PMID 35748290, 2022). "Our results also provide new evidence that midlife circulating TREM2 predicts dementia at older ages." (PMID 34338426, 2022). "High risk variants of TREM2 (loss of function) identified in neurodegenerative disorders and upregulation of TREM2 gene expression in AD and other dementias suggest a beneficial role." (PMID 34205235, 2021). "In the case of NHD, rare loss-of-function variants in TREM2 or DAP12 result in osteoporosis and presenile dementia." (PMID 33568650, 2021). "For this phenomenon, vertical pleiotropy can be the case where TREM2/DAP12 variants cause osteoporosis in the age of 20–30 years, which in turn causes presenile dementia in later life." (PMID 33568650, 2021). "Previous studies have shown that the effect of the APOE gene on the risk of cognitive decline and dementia was modified by other genetic factors, including ABCA7, SORL1, PICALM, CR1, BIN1, and TREM2, showing complex gene-gene interactions." (PMID 34214049, 2021). "We report two novel variants on chromosome 6 genes POLH and TREM2 in the same patient, associated with a phenotype of XPV and early‐onset dementia." (PMID 32935933, 2020).
dementia (continued). "We report a case of a patient with xeroderma pigmentosum variant type who developed early‐onset dementia, in which two novel gene variants in POLH and TREM2 were found." (PMID 32935933, 2020). "This study contributes to the increasing evidence that brain cholesterol metabolism, ApoE, and TREM2 signaling are major players in the pathogenesis of AD-related dementias, including CAA." (PMID 32711525, 2020). "Soluble TREM2 protein levels declined and p-Tau level increased in DS serum with age and dementia progression." (PMID 30909239, 2019). "While this disease is characterized by early onset presenile dementia followed by delayed bone symptoms in patients carrying TREM2 mutations, patients with mutations in DAP12 display an early onset combination of presenile dementia and systemic bone cysts." (PMID 20721346, 2010). "Among participants without dementia, carrying any of the two TREM2 variants was associated with higher NEFL levels (Beta = 0.06, P = 5.8e-5), but not among participants who later developed dementia." (PMID 40061357, 2025). "AL002, a humanized monoclonal antibody, has demonstrated the capacity to elevate cell survival and proliferation through the activation of TREM2 signaling, thereby counteracting dementia potentially arising from compromised TREM2 functionality, while simultaneously invigorating microglial activity." (PMID 40552184, 2025). "Carriers of TREM2 risk variants without incident dementia have consistently elevated NEFL compared to non-carriers, even in midlife." (PMID 40061357, 2025). "Moreover, a mutant Itm2b dementia mouse model exhibits elevated Trem2-CTF and sTrem2, mirroring sTREM2 increases in AD patients." (PMID 38347225, 2024). "Trem2−/− mice do not exhibit neurodegenerative pathology but TREM2 loss-of-function sensitises the carrier to the development of disease in dementia models." (PMID 35333324, 2022). "Thus, our observations here suggest recruitment of TREM2+ cells independently from the factors that impact on development of dementia after stroke." (PMID 35748290, 2022). "Microglia, not astrocytes, express TREM2, whose mutation is highly associated with dementia through microglial hypoactivation in humans." (PMID 35142399, 2022). "Meanwhile, clinical data also suggested that CSF Trem2 levels are highly associated with post‐surgery delirium in patients without pre‐existing dementia." (PMID 34990087, 2022). "Homozygous loss of function mutations in TREM2 or in its cognate signaling element DAP12, has been reported to cause Nasu Hakola disease (NHD), an autosomal recessive disorder, characterized by early onset dementia and bone cysts." (PMID 33115519, 2020). "Here, we report for the first time the generation and characterization of a model of LOAD using lymphoblast-derived iPSCs from patients harboring the R47H mutation in TREM2, as well as from control individuals without dementia." (PMID 32630447, 2020). "This means that TREM2 mutation can cause an aberrant innate immune cell signaling that contributes to several neurodegenerative pathway initiations and propagations, including those involved in FTD and PD-dementia." (PMID 32908482, 2020). "Loss-of-function mutations in both TREM2 and DAP12 have been reported to cause NHD/PLOSL, an autosomal recessive disorder in which patients suffer from systemic bone cysts and progressive encephalopathy resulting in presenile dementia." (PMID 26337043, 2015). "Another mutation affecting the 5’ consensus donor splice site in intron 1of TREM2 had been previously implicated in early-onset dementia without bone cysts in a Lebanese family." (PMID 23800361, 2013). "TREM2 is an important player in the immune response and loss-of-function mutations in TREM2 have been demonstrated to cause a spectrum of dementia-like phenotypes with or without bone cysts." (PMID 23800361, 2013).